CXCL1 (C-X-C motif chemokine ligand 1)
Diseases named in the same sentence as CXCL1 in open-access papers (continued):
Sharing a sentence is not in itself a finding about the gene and the disease.
Hypertension (continued). "Patients with hypertensive retinopathy have higher levels of CXCL1 in their blood than patients with hypertension but without hypertensive retinopathy and healthy individuals." (PMID 36613652, 2022). "Moreover, our recent data indicate that the up‐regulation of CXCL1 or CXCR2 contributes to the Ang II‐induced recruitment of monocytes and macrophages, hypertension, vascular injury and cardiac hypertrophic remodelling." (PMID 32812337, 2020). "C-X-C Motif Chemokine Ligand 1(CXCL1)/CXCR2 biological axis plays an important role in the modulation of theadhesion and aggregation of macrophages in the aortic wall, and mediates theinflammatory response in vascular diseases such as hypertension andatherosclerosis." (PMID 33605308, 2021).
pancreatic ductal adenocarcinoma (14 papers, 2019 to 2025). An infiltrating adenocarcinoma that arises from the epithelial cells of the pancreas. "Notably, CXCL1 has a well characterized role in pancreatic ductal adenocarcinoma; it promotes myeloid cell recruitment and is associated with immunosuppressive macrophage infiltration." (PMID 38542481, 2024). "However, the necroptotic cells of pancreatic ductal adenocarcinoma enhanced the immunosuppressive function of tumor-associated macrophage (TAM) by C-X-C motif chemokine ligand 1 (CXCL1) and Mincle signaling." (PMID 35312867, 2022). "In pancreatic ductal adenocarcinoma in mice, necroptosis induces an immunosuppressive tumor microenvironment via CXCL1 expression, contributing to cancer progression." (PMID 39623066, 2025). "In particular, macrophages produce significant amounts of CXCL1 at the metastatic site of pancreatic ductal adenocarcinoma." (PMID 37408240, 2023). "Through activation of the receptor CXCR2, CXCL1 increases pancreatic ductal adenocarcinoma proliferation." (PMID 37408240, 2023). "It has been proven that CXCL1-promoted macrophage-induced adaptive immunosuppression can be induced by necroptosis to advance the occurrence of pancreatic ductal adenocarcinoma." (PMID 36046241, 2022). "In pancreatic ductal adenocarcinoma cells, there is an induction of CXCL1 expression by IL-35, which is associated with the direct binding of the STAT1/STAT4 heterodimer to the CXCL1 promoter." (PMID 35054978, 2022). "The significance of p63 in CXCL1 expression was found in tumors, particularly in pancreatic ductal adenocarcinoma cells." (PMID 35054978, 2022). "In advanced pancreatic ductal adenocarcinoma tumors, CXCL1 also has pro-tumorigenic properties." (PMID 37408240, 2023). "This has important implications for the recurrence of this cancer following chemotherapy with gemcitabine, where an increase is shown in the expression of CXCR2 ligands, including CXCL1, in pancreatic ductal adenocarcinoma and in the metastatic site of this tumor." (PMID 37408240, 2023). "In pancreatic ductal adenocarcinoma (PDA), the necroptotic pathway was found to promote oncogenesis through releasing the chemokine (C-X-C motif) ligand 1 (CXCL1) and 130 kDa Sin3-associated polypeptide (SAP-130), which induce immune-suppression in the tumor microenvironment." (PMID 31922095, 2019). "Also, necroptosis-induced chemokine ligand 1 (CXCL1) expression may be crucial for the progression of pancreatic ductal adenocarcinoma and promote a macrophage-induced adaptive immune response." (PMID 37993258, 2023). "Some anticancer drugs, such as gemcitabine, increase the expression of CXCL1 and CXCL2 in pancreatic ductal adenocarcinoma tumor cells." (PMID 37408240, 2023). "They found that IL-35 increased the aggregation of monocytes and the expression of CXCL-1 and CXCL-8, which promoted angiogenesis in pancreatic ductal carcinoma." (PMID 33041668, 2020). "CXCL1 induces the recruitment of neutrophils into the tumor niche of pancreatic ductal adenocarcinoma and G-MDSCs but not monocytes and macrophages." (PMID 37408240, 2023). "However, other studies have shown that in humans, CXCL1 expression in pancreatic ductal adenocarcinoma tumors is not different relative to healthy tissue." (PMID 37408240, 2023).
Alzheimer disease (13 papers, 2013 to 2025). A progressive, neurodegenerative disease characterized by loss of function and death of nerve cells in several areas of the brain leading to loss of cognitive function such as memory and language. "Recent studies have highlighted the association between increased CXCL1 levels in the brains of individuals with Alzheimer’s disease." (PMID 37373050, 2023). "This is supporting to our findings and together, it suggests a plausible causal role of CXCL1 in the pathogenesis of Alzheimer’s disease." (PMID 35580794, 2022). "For example, CXCL1 is upregulated in the aging prostate, it is known to inhibit muscle repair and regeneration, and it is implicated in Alzheimer’s disease." (PMID 36100892, 2022). "We observed some evidence for a detrimental effect of greater levels of CTACK (CCL27), MIP-1b (CCL4), Eotaxin, GROa (CXCL1), MIG (CXCL9), IL-8 and IL-2 on the risk of Alzheimer’s disease." (PMID 35580794, 2022). "Another component of Alzheimer’s disease is neuroinflammation, including increased CXCL1 expression and action." (PMID 35457023, 2022). "Notably, individuals with Alzheimer’s disease also exhibit increased CXCL1 expression in blood monocytes." (PMID 37373050, 2023). "In Alzheimer’s disease patients, CXCL1 levels are elevated in cerebrospinal fluid and the brain." (PMID 35457023, 2022). "CXCL1 is produced by neurons in the brain of Alzheimer’s disease patients." (PMID 35457023, 2022). "CXCL1 may also participate in mechanisms that inhibit the progression of Alzheimer’s disease." (PMID 35457023, 2022). "Nevertheless, their physiologic role could degenerate into neurotoxic effects during chronic neuroinflammation, as demonstrated in a murine model of Alzheimer’s disease for CCL2/CCR2 and CXCL1/CXCR2." (PMID 40801605, 2025). "CTACK (CCL4), MIG (CXCL9), GROa (CXCL1), MIP-1b (CCL4), Eotaxin (CCL11) and IL-8 belong to the chemokine family and evidence suggest that they could potentially play a role in Alzheimer’s disease." (PMID 35580794, 2022). "We found that NSUN7, SLC6A8, CXCL1 and LCN8 were significantly different in groups B compared to A, and SLC1A3 and LCN8 were significantly different in groups C compared to A. NSUN7, a m5C RNA methyltransferase gene, is differentially expressed in Alzheimer's disease patients." (PMID 39185136, 2024). "Previous studies illustrated that Th17 cells were found in the vicinity of neuritis plaques in AD brains, along with increased pro-inflammatory cytokines (IL-1β, IL-6, CXCL1, and TNF-α) in peripheral blood, which may contribute to the development of Alzheimer’s disease." (PMID 35669784, 2022).
Cirrhosis (13 papers, 2013 to 2025). A chronic disorder of the liver in which liver tissue becomes scarred and is partially replaced by regenerative nodules and fibrotic tissue resulting in loss of liver function. "CXCL1 expression is also elevated in acute injury and chronic liver diseases, frequently associated with fibrosis and cirrhosis." (PMID 39595015, 2024). "First, the expression of CXCL1 in liver tissue was found to be positively associated with cirrhosis, and the levels of CXCL1 expression in tumours were similar between HCC tissue and adjacent nontumor liver tissue." (PMID 37037815, 2023). "Although our study is limited by its cross-sectional design it nevertheless provides first experimental evidence suggesting the CXCL1 rs4074 polymorphism modulates the risk for cirrhosis in Caucasian patients with high alcohol consumption." (PMID 24260493, 2013). "The present study suggests that the rs4074 single nucleotide polymorphism within the CXCL1 gene is associated with increased CXCL1 blood levels and increased risk for development of cirrhosis in alcoholics." (PMID 24260493, 2013). "Numerous intrahepatic chemokines and their receptors are up-regulated in alcohol-induced liver fibrosis, and a genetic polymorphism in the CXCL1 gene (rs4074) has recently been identified as an independent factor predisposing to cirrhosis in patients of European descent with chronic hepatitis C." (PMID 24260493, 2013). "Here, we explored the protumor effects of CXCL1, a commonly elevated inflammatory chemokine in cirrhosis, in HCC." (PMID 37037815, 2023). "CXCL1, a chemokine that acts as an important proinflammatory mediator by driving the migration of a variety of immune cells in cirrhosis has been fully explored and found to specifically bind to CXCR2." (PMID 37037815, 2023). "A positive relationship between cirrhosis and CXCL1 levels was also found in the analysis paired adjacent tissues." (PMID 37037815, 2023). "In this study, CXCL1, a common chemokine correlated with liver inflammation and cirrhosis, was explored for its protumor function related to macrophages in HCC." (PMID 37037815, 2023). "Accordingly, the frequency of the CXCL1 rs4074 A allele was significantly higher in the cirrhotic patients than in the subjects without cirrhosis (41.4% vs. 33.9%, OR=1.38, 95% CI:1.14–1.66, p=0.001)." (PMID 24260493, 2013). "The expression level of CXCL1 was higher in most HCC patient tissue samples than in corresponding normal samples and was positively related to cirrhosis and tumour microvascular invasion." (PMID 37037815, 2023). "Serum CXCL1 levels were measured in healthy controls, patients with chronic HBV, patients with HBV-related compensated cirrhosis, and patients with HBV-ACLF." (PMID 34395462, 2021). "In our previously published study, we showed that serum CXCL1 levels and neutrophil counts were significantly higher in patients with HBV-ACLF than in healthy individuals and patients with chronic HBV or HBV-ACLF–compensated cirrhosis." (PMID 37708451, 2023). "In our assessment, CXCL1 levels corresponded with HBV-cirrhosis, while CXCL8 was characteristic of non-viral etiologies." (PMID 36230823, 2022). "Previous studies have shown that CXCL1 is a proinflammatory cytokine in various viral and nonviral hepatitis types and is positively correlated with chronic hepatocyte injury and the progression of cirrhosis." (PMID 37037815, 2023). "For example, chemotaxis towards CXCL8, CXCL1 or casein, and phagocytosis of C. albicans are not impaired in cirrhosis, which might indicate that functional defects in cirrhosis are limited to certain pathways." (PMID 37822786, 2023). "A closer look at the cirrhosis etiologies revealed that HBV-cirrhosis had the highest number of uniquely augmented cytokines with a prominent role for high levels of the NK and NKT cell cytokine IFN-γ, the apoptosis marker TRAIL and the neutrophil attracting CXCL1." (PMID 36230823, 2022).
Cirrhosis (continued). "CXCL1, which is secreted from LSECs following mechanical stretching, triggers formation of sinusoidal microthrombi, thereby increasing portal pressure independent of cirrhosis." (PMID 31752395, 2019). "Upon detailed assessment, cytokine levels and cirrhosis etiology revealed that HBV-cirrhosis—regardless of antiviral therapy—had a 3-fold increase in IFN-γ, TRAIL and CXCL1 (GRO-α) levels and up to 3-fold decrease in MMP-2, CXCL12, IL2RA, IL-6Rα, CCL2 (MCP1) and CCL21 (6kine) levels." (PMID 36230823, 2022).
encephalitis (13 papers, 2011 to 2025). An acute inflammatory process affecting the brain parenchyma. "We next utilized neutralizing antibodies to evaluate the roles of CXCL1 and IL-6 in EV-A71 encephalitis." (PMID 39679722, 2025). "Therefore, we speculate that astrocyte-derived CXCL1 drives neutrophil transmigration, and future experiments should be performed to elucidate the mechanisms underlying neutrophil-related alterations in EV-A71 encephalitis." (PMID 39679722, 2025). "In a murine model of viral encephalitis, astrocyte- and neuron-derived CXCL1, through its receptor CXCR2, facilitates neutrophil transmigration and blood–brain barrier (BBB) permeability." (PMID 40243443, 2025). "CXCL1 expression in the CNS has been demonstrated to be associated with breakdown of the BBB and the development of viral encephalitis." (PMID 39679722, 2025). "In a murine model of viral encephalitis, blocking CXCL1-dependent signalling leads to reduced BBB permeability, neutrophil penetration and mortality." (PMID 37765263, 2023). "IL-17F and CXCL1 CSF concentrations correlated with neutrophil count and CXCL1 concentration was higher in patients with encephalitis." (PMID 29678185, 2018). "We next evaluated the potential therapeutic value of neutralizing CXCL1 in EV-A71 encephalitis." (PMID 39679722, 2025). "Moreover, in FIRES Th1-associated cytokines and chemokines, as well as IL-6, CCL2, CCL19, and CXCL1, resulted elevated when compared to the levels observed in encephalitis, which involved a broader network of cytokines/chemokines." (PMID 38078329, 2023). "In the JE model, the severity of encephalitis is related to skewing of the specific cellular response from regulatory (Treg) to Th17-type, with the increased IL-17, CXCL1, and CXCL2 expression promoting the CNS infiltration by granulocytes, monocytes, and cytotoxic CD8+ lymphocytes." (PMID 29678185, 2018). "RVFV infection with 1 PFU induced Cxcl1 approximately 10-fold while 5 PFU induced these transcripts by ~100-fold, consistent with previous studies of RVFV encephalitis." (PMID 38935789, 2024). "The chemokine Gro-KC in rats (CXCL1; related to IL-8 in humans) attracts neutrophils, utilizes CXCR2 as its receptor, and was found in high levels in the brains of rats dying from RVF encephalitis." (PMID 31220182, 2019). "Macrophages rapidly upregulate CXCL1 and CXCL2 expression, while neurons and astrocytes also produce CXCL1 in vivo following HSV-1 infection which is the most common cause of viral encephalitis, although not a flavivirus." (PMID 40918112, 2025). "In vitro, human brain microvasculature endothelial cells secrete CXCL1 and CXCL5 and favor transmigration of neutrophils under IL-22 stimulation, confirming that findings from animal experiments may apply to human encephalitis." (PMID 29678185, 2018).
ischemia (13 papers, 2010 to 2025). A hypoperfusion of the BLOOD through an organ or tissue caused by a PATHOLOGIC CONSTRICTION or obstruction of its BLOOD VESSELS, or an absence of BLOOD CIRCULATION. "Similarly, hepatic IRF-8 increase aggravates liver ischemia/reperfusion injury in mice, and the underlying mechanism is related to elevating CXCL1/9 production and neutrophil recruitment." (PMID 35637950, 2022). "We found that endothelial markers (Angptl4), and pericyte marker (Cyp1b1, Emp1, S1pr3, Serping1, and Cxcl1) were upregulated in prolonged ischemia." (PMID 35154109, 2022). "Pre-treatment with candesartan or aliskiren attenuated this increase of CXCL1 expression 24 h post-ischemia." (PMID 21124781, 2010). "As a crucial mediator in the inflammatory response, CXCL1 has been found to activate neutrophils when they attach to immune complexes and may potentially inflict ischemia injury on surrounding tissues." (PMID 40630894, 2025). "In addition, dectin-1 affects Syk, NF-κB, and p38-associated pathways, which regulates neutrophil recruitment through the regulation of the expression and secretion of CXCL1 and G-CSF after ischemia-reperfusion injury." (PMID 34094602, 2021). "In addition to MCP-1, IL-6 mRNA expression in the saline-pretreated group also increased significantly after ischemia and this elevation persisted along with a significant increase in the neutrophil chemoattractant, KC (CXCL1) seen at 24 h reperfusion." (PMID 28182087, 2017). "However, the concentration of three cytokines, KC/GRO (CXCL1), IL-6, and TNFα, were showed to be significantly increased in the coronary effluents of the hearts after IR injury (after ischemia and 60 min of reperfusion) compared with the basal conditions (collected at 10 min stabilization, basal)." (PMID 34616778, 2021). "In addition, overexpression of renal level of CXCL1 was found to worsen renal function in wild-type mice, which could aid in exacerbated inflammation following renal ischemia-reperfusion injury, a key reason for intrinsic acute renal failure." (PMID 34462420, 2021). "In a mouse model in which ischemia was pharmacologically induced, it was observed that TREM-1 promotes the production of IL-1β, IL-18, IL-6, CXCL-2, MCP-1, and CXCL-1 in microglia." (PMID 39062850, 2024). "Consistently, we found that ischemia-induced TREM-1 promoted IL-1β, IL-18, IL-6, CXCL-2, MCP-1, and CXCL-1 productions in microglia as well as the expression of MPO and ICAM-1 following ischemic injury." (PMID 31324751, 2019). "Astrocytes activated by ischemia and anoxia secrete many pro- and anti-inflammatory factors, such as IL-1β, IL-6, TNF-α, TGF-β, VEGF-A, MCP-1 CXCL-1, MMP-2, and MMP-9, which influence BBB integrity." (PMID 31779652, 2019). "In the setting of MI, chemokines that recruit PMNs to sites of ischemia include macrophage inflammatory protein-2α (MIP-2α, CXCL2, GRO β), leukotriene B4 (LTB4), CINC-1 (CXCL1, GRO α, KC), IL-8 (CXCL8), and complement 5a." (PMID 23731794, 2013).
acute kidney injury (12 papers, 2011 to 2026). Sudden and sustained deterioration of the kidney function characterized by decreased glomerular filtration rate, increased serum creatinine or oliguria. "This study identifies a molecular mechanism of the O-linked N-acetylglucosamine transferase (OGT)-mediated enhancer of zeste homolog 2 (EZH2)/krüppel-like factor 2 (KLF2)/chemokine (C-X-C motif) ligand 1 (CXCL1) axis underlying the hypercalcemia-induced nerve injury in renal failure." (PMID 34462420, 2021). "Taken together, silencing OGT downregulates EZH2, which increases the expression of KLF2 and then decreases the expression of CXCL1, thus alleviating hypercalcemia-induced nerve injury in renal failure." (PMID 34462420, 2021). "For example, miR-15a, miR-15b, and miR-16 are able to inhibit the expression of CXCL1 and mediate the therapeutic effects of exosomes from hUC-MSCs in models of acute kidney injury." (PMID 31779691, 2019). "In addition, IL-33 promotes acute kidney injury through CD4 T cell-mediated production of CXCL1." (PMID 27579324, 2016). "In the current study, we explored the regulatory mechanism of OGT in hypercalcemia-induced nerve injury in renal failure and found that OGT promotes this injury by regulating the EZH2/KLF2/CXCL1 axis." (PMID 34462420, 2021). "Another role for IL-33 was demonstrated by Akcay and colleagues, finding that IL-33 promotes acute kidney injury (AKI), through CD4 T cell-mediated production of the pro-inflammatory chemokine CXCL1." (PMID 30769901, 2019). "For example, recombinant IL-33 (rIL-33) treatment can exacerbate cisplatin-induced acute kidney injury by increasing CD4+ T cell infiltration, CXCL1 production, and acute tubular necrosis." (PMID 26943125, 2016). "CXCL1 and CXCL2, were recently shown to be essential for neutrophil recruitment which is key to acute renal failure developing in Stx2-challenged LPS-treated mice." (PMID 21731756, 2011). "Another report noted that mice lacking CXCL1 exhibited decreased survival with enhanced Candida growth in the kidneys and renal failure." (PMID 41294483, 2025).